Y_RNA (Y RNA )
Gene: Miscellaneous RNA gene on chromosome X (53,324,562 to 53,324,674, forward strand). Ensembl gene ENSG00000207408.
Homologues: Orthologues: chimpanzee Y_RNA (99% identical), macaque Y_RNA (98% identical). Paralogues in human: RNY1 (91% identical), Y_RNA (90% identical), RNY1P11 (88% identical), Y_RNA (88% identical), RNY1P8 (87% identical), Y_RNA (87% identical), RNY1P5 (86% identical), Y_RNA (86% identical), Y_RNA (85% identical), RNY1P15 (84% identical), Y_RNA (84% identical), RNY1P10 (83% identical), and 98 more.